EGF (epidermal growth factor)
Diseases named in the same sentence as EGF in open-access papers (continued):
Sharing a sentence is not in itself a finding about the gene and the disease.
cancer (continued). "Using the Cal-27 and Cal-33 cancer cell lines, we observed that proNGF reduces the effects of EGF on cell growth by inducing the internalization of its receptor." (PMID 37576898, 2023). "Another crucial category, TGF, a member of the epidermal growth factor (EGF) family, promotes cell growth, stimulates the development of epithelia, and has a role in cancer and angiogenesis." (PMID 37895012, 2023). "Another cancer-related pathway which was addressed after 12 h of AV25R exposure is the EGF/EGFR signaling pathway." (PMID 38138609, 2023). "Sialidase NEU3, a key glycosidase for ganglioside degradation, is upregulated in various human cancers, increasing cell invasion, motility, and survival of cancer cells, possibly through activating epidermal growth factor (EGF) signaling." (PMID 38203236, 2023). "CXCL1 expression in cancer cells is also elevated by secretory factors such as epidermal growth factor (EGF), IL-17, protease-activated receptor 1 (PAR1), and TNF-α." (PMID 37108425, 2023). "These gradients are the result of a balance between cancer cells' EGF uptake in the loading channel and the restricted EGF diffusion through the migration channels from the fresh media in the external chamber in detail." (PMID 38155198, 2023). "In contrast, we also observed a modest decrease in the expression of EGF, consistent among different cancer types." (PMID 38067195, 2023). "PBMC from healthy donors were incubated with TNFα, TGFβ, rapamycin, PMA, EGF or with the conditioned media (CM) of cancer cells (HT-29), containing several TME factors, including cytokines, growth factors and chemokines." (PMID 37426665, 2023). "The role of epidermal growth factor (EGF) signaling via its receptor in the plasma membrane (EGFR) in cancer cell proliferation is well known." (PMID 37834119, 2023). "There is evidence from both experimental and clinical investigations suggesting that the epidermal growth factor (EGF) plays a significant role as an oncogenic growth factor in cancer." (PMID 36902446, 2023). "In breast cancer, EGF signaling regulates cancer progression through different signaling mechanisms such as cell motility and proliferation, regardless of the ER participation." (PMID 37681860, 2023). "M2 macrophages release high concentrations of epidermal growth factor (EGF) and induce angiogenesis and the invasion and metastasis of cancer cells through the activation of an EGF receptor (EGFR)." (PMID 36831623, 2023). "By elucidating the interplay between EGF and NPs uptake, this study contributes to the advancement of targeted therapeutic strategies and the development of more effective treatments for cancer." (PMID 37954478, 2023). "First, the concentration optimization of specific blockers of estrogen (in MCF7) and epidermal growth factor (in MDA-MB-231) receptors in cancer cells was performed." (PMID 36982173, 2023). "EGF is a common mitogenic factor that elicits different downstream signaling pathways depends on different types of cancer or cell lines." (PMID 37309001, 2023). "Subsequent studies verified that EGF is a potent cell growth factor for almost all epidermal cells and that hyper-signaling of EGF or EGF receptors is involved in cancer growth and metastasis." (PMID 36830741, 2023). "We found a similar positive correlation between LGALS3 and cancer-specific EMT signature scores in OVCA420 cells treated with either EGF (R2 = 0.01) or TNF-α (R2 = 0.02)." (PMID 38086828, 2023). "It is well established that the epidermal growth factor (EGF) contributes to a number of processes which are important to cancer development and progression." (PMID 36594087, 2023). "These cancers all have in common epidermal growth factor (EGF) receptor overexpression/amplification, such as EGFR and ERBB2." (PMID 38041118, 2023).
cancer (continued). "A study conducted on individuals before and after surgery and intraoperative radiotherapy (IORT) showed a positive regulation of miR-223 expression in the mammary gland after IORT, resulting in local EGF release and a decreased survival of cancer cells." (PMID 37628945, 2023). "Cancer cells produce diffusible cancer growth factors (CGFs) such as nerve growth factor, epidermal growth factor or platelet-derived growth factor that promote the growth of the conspecifics and suppress the normal cells (alien to the cancer cells)." (PMID 38111808, 2023). "Some of these pathways are part of the EGF system signaling network, which becomes hyperactivated by various mechanisms and participates in cancer pathogenesis." (PMID 37873809, 2023). "Simultaneously, cancer cells produce colony-stimulating factor-1 (CSF-1) that strenghtens EGF expression in macrophages." (PMID 36835266, 2023). "Another major factor in various human cancers is the epidermal growth factor (EGF) and its correlating receptor, the epidermal growth factor receptor (EGFR)." (PMID 37623256, 2023). "Amphiregulin (AREG) gene, which belongs to the epidermal growth factor (EGF) family, is overexpressed in many cancer tissues." (PMID 36843929, 2023). "Epidermal growth factor (EGF) secreted from these cells in spheroids promotes cancer cell growth and survival." (PMID 37180125, 2023). "EGF is characterized by overexpression in various cancer cell types, and binding to its receptor EGFR triggers a series of important processes ultimately affecting cell growth, differentiation, and proliferation." (PMID 38027211, 2023). "LY6K‐depletion in HeLa and SiHa cancer cells suppressed EGF‐induced proliferation and TGF‐β‐enhanced migration and invasion." (PMID 37076981, 2023). "We demonstrate the properties of filter inference using examples from early cancer growth modelling and from epidermal growth factor signalling pathway modelling." (PMID 37216399, 2023). "The biological behavior of cancer cells to generate EMT will be regulated by a large number of growth factors and cytokines including TGF-β, IL-6, EGF, VEGF and HGF, secreted from Cancer-associated fibroblasts (CAFs)." (PMID 37880742, 2023). "Oxidative stress promotes the expression of matrix metalloproteinases, adhesion molecules, and epidermal growth factor and its receptor, which in turn promotes cancer progression and metastasis." (PMID 38067221, 2023). "At the same time, we also found positively selected differentially edited sites in a series of cancer immune genes, including EGF, IGF1R, and PIK3CD." (PMID 36895481, 2023). "EGF secreted by TAMs activates the EGFR/extracellular signal-regulated kinase 1/2 signal pathway in some types of cancer cells, which results in the promotion of EMT." (PMID 38033495, 2023). "According to research, TGF or EGF, which are produced by cancer cells themselves, can auto-stimulate EGFRs in cancer cells, which results in uncontrolled growth of cancer cells." (PMID 38090376, 2023). "Plasma EGF is significantly higher in cancer patients than in those with benign colorectal conditions." (PMID 36978925, 2023). "In particular, the epidermal growth factor (EGF) is one of the most researched moieties with which to decorate NPs for cancer therapy." (PMID 36768820, 2023). "CSF-1, in turn, recruits and activates TAMs to further secrete EGF, indicating the presence of an EGF/CSF-1 positive feedback loop between TAMs and cancer cells." (PMID 37445965, 2023). "Our studies of the role of EGF/CSN6 in hindering FBXW7β-mediated FASN ubiquitination reveal rational therapy for cancer intervention." (PMID 37202390, 2023). "BMMs were stimulated by four common components secreted by cancer cells as reported by previous studies, including EGF, IL-11, CTGF and PTHrP." (PMID 36593458, 2023). "EGF, a member of the positive regulation of protein tyrosine kinase activity, was identified as a stimulator of cancer cells." (PMID 37991016, 2023).
cancer (continued). "Mutations of EGF and EGFR were each found in only a single sample from our cohort and did not coincide with sites that are altered frequently in human cancers." (PMID 37079639, 2023). "The vaccine is intended to induce a humoral response against EGF, which can prevent the binding of the ligand to the receptor in the cancer cells, thus blocking the pro-tumoral signals." (PMID 38304035, 2023). "Spheroid body culture aims to enrich cancer stem cells by using low attachment conditions and some growth factors, such as basic fibroblast growth factor and epidermal growth factor to support the spheroid formation in serum-free spheroid culture." (PMID 37529165, 2023). "We find that the directional decisions of cancer cells moving through bifurcating channels in response to self-generated epidermal growth factor (EGF) gradients require the presence of glutamine in the culture media." (PMID 37205536, 2023). "Macrophages, by expressing EGF, promote protrusion formation in cancer cells, therefore enhancing cancer invasion." (PMID 36835266, 2023). "BPGAP1 recruits the RacGEF Vav1 under epidermal growth factor (EGF) stimulation and activates Rac1, leading to polarized cell motility, spreading, invadopodium formation, and cell extravasation and promotes cancer cell migration." (PMID 36598812, 2023). "Very little is known about the effects of direct EGF stimulation on cancer cells in the regulation of MHC I/-II." (PMID 38067396, 2023). "Here, we demonstrate a CLEM workflow using individual small AuNPs as single probes of the epidermal growth factor (EGF) protein in mammalian cancer cells, imaged by FWM in LM and correlatively by transmission EM." (PMID 36977682, 2023). "Here, we design microfluidic devices with a series of bifurcating channels to study the directionality of cancer cells during the migration in self-generated EGF gradients." (PMID 38155198, 2023). "TAMs produce EGF (epidermal growth factor) which enhances the invasion and motility of cancer cells through increasing matrix degradation." (PMID 37325423, 2023). "HT29 carcinoma cells were treated with nine different combinations of epidermal growth factor (EGF) and insulin to induce apoptosis." (PMID 36768586, 2023). "The data provided here is a comparison of a normal and a cancer cell line in response to the following growth factors, EGF, TGFα, TGFβ-1, VEGF, and NGF, and a specific inhibitor of Akt, MK2206." (PMID 35681586, 2022). "Treatment of EGFR-expressing cancer cells with EGF shows increased hTERT expression, while EGFR inhibition using AG 1478 shows the reverse effect." (PMID 35974340, 2022). "According to the previous studies, M2 macrophages interact with the surrounding cells through secreting the growth factors including EGF, PDGF, VEGF, and TGF-β1, which are considered to be closely associated cancer progression." (PMID 36046687, 2022). "EGF efficiently addressed the nanoparticles against EGFR-overexpressing cancer cells, showing superior phototoxicity when compared to free photosensitizers." (PMID 35213974, 2022). "It has been reported that CDCP1 is crucial for the activation of RAS in cancer, and participates in multiple oncogenic pathways, such as EGF signaling and HGF signaling." (PMID 36090897, 2022). "Bioconjugates of EGF with disulfochloride aluminum phthalocyanine [Pc(Al)] and disulfochloride cobalt phthalocyanine [Pc(Co)] were prepared, using EGF as a vector for targeted delivery of the phthalocyanines to cancer cells." (PMID 35213974, 2022). "The Epidermal Growth Factor (EGF) receptor is highly present in cancer cells and is selective for its ligand, EGF." (PMID 35778747, 2022). "Thankfully, EGF promoted cancer cell adhesion, proliferation, and migration, and cancer spheroids were observed only after 3-day culture." (PMID 36015599, 2022). "EGF/AKT signaling is highly active in many types of cancers, and it becomes a critical therapeutic target for anti-cancer drugs." (PMID 36473865, 2022).
cancer (continued). "Mechanically, because of molecular structural similarity with EGF, the association between SPINK1 and EGFR has been studied in many cancers." (PMID 36053457, 2022). "Another form of treatment involves binding to the EGF directly to create a conformational change, decreasing the amount of available EGF in the bloodstream for cancer cell binding." (PMID 36059606, 2022). "Overexpression of various growth factors, such as transforming growth factor (TGF), epidermal growth factor (EGF), fibroblast growth factor (FGF), and HIF-1, cause EMT in cancer cells." (PMID 36142793, 2022). "There are limited data available on the role of EGF in pulmonary vascular remodeling secondary to hypoxia, although a role for EGF in cancer has been well established." (PMID 35674115, 2022). "In this work, we disclose a mechanism of EGF action in the regulation of large-sized glucosomes in cancer cells." (PMID 35122791, 2022). "AREG proteins can inhibit the growth of certain aggressive cancer cell lines and promote the growth of normal epithelial cells by interacting with EGF/TGF-α receptors." (PMID 36119517, 2022). "As the AKT pathway has been shown to be stimulated in cancer cells by growth factors, we chose to use EGF as a mitogen to stimulate the AKT1 pathway in MCF-7 cells." (PMID 35892586, 2022). "Ultimately, the decrease in EGF in the bloodstream starves cancer cells, directly deregulating critical pathways involved in tumor growth, signaling, and differentiation." (PMID 36059606, 2022). "Src-mediated AR Tyr-534 phosphorylation is known to induce AR nuclear translocation, active its transcriptional activity, and drive cancer cell growth in response to EGF stimulation." (PMID 35595729, 2022). "Since various growth factors, such as EGF, can activate PIP3 production, it is likely that ARHGEF7 more widely contributes to cancer invasion/metastasis caused by amplification and/or mutation of various growth factor receptors." (PMID 35085554, 2022). "We found that optimal dia-PASEF window placement facilitates in-depth phosphoproteomics with very high sensitivity, quantifying more than 35,000 phosphosites in a human cancer cell line stimulated with an epidermal growth factor in triplicate 21 min runs." (PMID 35944843, 2022). "AQP3, induced by EGF, can promote growth and cellular migration of various cancer cell lines through promoting H2O2 flux, which itself can trigger cell proliferation and migration." (PMID 35847914, 2022). "Recent studies have argued for an antagonistic cross-talk between the EGF signal transduction pathway and type I interferon response in cancer cells emerging through the activity of HER2, a co-receptor of EGFR and an important drug target." (PMID 35563635, 2022). "Fourthly, since EGF is of clinical importance in cancer therapeutics, we targeted EGF activities in the presence of different drugs and exposed cells to nNIR." (PMID 35203275, 2022). "EGF mediates cellular proliferation, differentiation, and survival and is involved in spheroid formation of cancer cells exposed to r-μg in space." (PMID 35252204, 2022). "In contrast, our study demonstrated that the MAPK4-AKT signaling cascade can be activated by both insulin and EGF, two key factors regulating physiology and diseases, including cancers." (PMID 35017531, 2022). "It was previously shown that CSF-1 initiates an EGF-dependent paracrine loop between cancer cells and macrophages that supports cancer cell invasion." (PMID 35998057, 2022). "Protein kinase C (PKC) and PI3K-Akt pathways also play a key role in EGF-induced cancer cell proliferation and migration in ROS-dependent pathways." (PMID 35799889, 2022). "Cancer cells harboring EGFR and downstream effector mutations in the signaling can be selected by EGF withdrawal." (PMID 36207749, 2022). "The CSF‐1 recruits and activates TAMs to further secrete EGF, which suggests the existence of an EGF/CSF‐1 positive feedback loop between TAMs and cancer cells." (PMID 34914196, 2022).
cancer (continued). "EGF has also been shown to positively affect telomerase activity as it is expected to be elevated in cancer cells." (PMID 35974340, 2022). "In this study, a multi-component bone matrix was fabricated using gelatin, hydroxyapatite (HAp), and epidermal growth factor (EGF) as raw materials to investigate how “acellular” bone matrix affects cancer cell homing in bone." (PMID 36015599, 2022). "Incubation of cancer cells with the free ligand EGF also reduced B-ASO binding (by competition) with the extracellular domain of EGFR, reaching boron cellular uptake levels of 14 and 8 μg B/g for A431 and U87 cell lines, respectively." (PMID 36499115, 2022). "Further, we found that the KLF4/ALDH1A1/EGF regulatory axis contributes to Cr(VI)‐induced carcinogenesis and promotes cancer cell differentiation." (PMID 36504325, 2022). "Human cancer tissues express high levels of growth factors and their receptors, such as EGF/EGFR, which exhibit autocrine or paracrine regulation of cancer growth." (PMID 35502895, 2022). "This study describes the first evidence of OTR expression affecting EGF-induced cancer cell migration capabilities and signalling." (PMID 35884900, 2022). "The role of miR-146a-5p in cancer is complex and cancer specific, however in prostate cancer it has been reported to induce a tumor suppressor function by stimulating downregulation of NF-kB and EGF signaling." (PMID 36671452, 2022). "CDR formation was examined in six cancer cell lines in response to epidermal growth factor (EGF) and insulin." (PMID 35799301, 2022). "For different culture periods, the effects of HAp, gelatin, and EGF on the cell adhesion, proliferation, 3D growth, and migration of cancer were evaluated." (PMID 36015599, 2022). "Quantitative analysis with rigorous washing of the spheroids showed that stable penetration of WT λ phages was in fact limited, and EGF decoration greatly enhanced and stabilized the accumulation within the cancer spheroid." (PMID 36591314, 2022). "Human EGF has been shown to retain its ability to bind to EGFR when fused to fd filamentous phage and the display of EGF on phage particles can direct the phage vectors to recognize EGFR-expressing cancer cells." (PMID 36591314, 2022). "Constructed with a substrate sensitive to MT1-MMP, this biosensor was able to capture drastic FRET changes induced by epidermal growth factor (EGF) in migrating cancer cells, via a process dependent upon an intact cytoskeletal network." (PMID 36338120, 2022). "Growth factors for cancer organoid culture include Wnt3A, R-spondin-1, TGF-β receptor inhibitor, epidermal growth factor, and Noggin, but the combination and concentration of these factors added to the media depend on the specific cancer type." (PMID 36713421, 2022). "We also enabled cancer cell-selective targeting by expressing EGF at the capsid surface to allow binding to the EGF receptor (EGFR)." (PMID 36591314, 2022). "Conversely, COX-2 is upregulated at sites of inflammation and by oncogenes, such as Ras and epidermal growth factor (EGF), in many cancers." (PMID 36234768, 2022). "A number of cytokines and growth factors, such as TGF-β, IL-10, IFN-γ and EGF function as regulators of MICA expression in different types of cancer cells." (PMID 35967396, 2022). "NF-κB is found to be activated in many cancers by several stimuli, including pro-inflammatory cytokines such as IL-1β, epidermal growth factor (EGF), T-cells and B-cell mitogens, among others." (PMID 35736190, 2022). "Nonetheless, it has remained elusive which EGF-triggered signaling pathways regulate the assembly of large-sized glucosomes in cancer cells." (PMID 35122791, 2022). "This indicated that our EGF-GHG scaffold created a similar hypoxia-driven cancer culture progression model under the dynamic culture state of normal oxygen supply." (PMID 36015599, 2022). "Lastly, EGF is important for cancer cell proliferation, angiogenesis, and metastasis in many types of cancer." (PMID 35628865, 2022).